IL4R (interleukin 4 receptor)
Diseases named in the same sentence as IL4R in open-access papers (continued):
Sharing a sentence is not in itself a finding about the gene and the disease.
breast cancer (36 papers, 2006 to 2025). A primary or metastatic malignant neoplasm involving the breast. "In breast cancer, upregulation of IL‐4/IL‐4R signaling has been associated with poor prognosis in both human and murine models." (PMID 33682324, 2021). "Furthermore, IL4R-positive BoMAMs have been shown in osteolytic lesions caused by human breast cancer metastasis." (PMID 36077870, 2022). "In addition, elevated expression of IL4Rα and/or IL13Rα1 were associated with poor prognosis of glioblastoma, mesothelioma, breast cancer, renal cell carcinoma, and oral cavity squamous cell carcinoma patients." (PMID 33419470, 2021). "The IL4/IL4Rα signaling axis enhances glucose and glutamine metabolism in breast cancer cells, thereby promoting tumor growth." (PMID 40656893, 2025). "Despite the role of IL-4/IL-4R in breast cancer progression in human and mouse models, we detected down-regulation of IL-4 in both 4T1 and MC4-L2 tumors." (PMID 39877637, 2025). "Studies have demonstrated that high expression of IL4R in breast cancer bone metastasis involves monocyte-derived macrophage subsets promoting metastasis in an IL4R-dependent manner." (PMID 40656893, 2025). "In order to efficiently deliver miRNAs targeting AQP5 to breast cancer cells, the researchers designed exosomes that express both miRNAs and a peptide targeting the interleukin-4 receptor, which is known to be highly expressed in breast cancer cells." (PMID 38136293, 2023). "We demonstrated that IL4 receptor (IL4rα)-null mice developed fewer and smaller lung metastasis in E0771-LG mammary cancer models of this disease." (PMID 36077870, 2022). "In summary, solid tumors such as breast cancer express IL‐4R on both tumor and immunosuppressive cells in the TME." (PMID 33682324, 2021). "Venmar and colleagues reported that IL-4Rα-downregulation decreased metastatic capacity in breast cancer." (PMID 33804263, 2021). "It has been shown that IL-4, via IL-4Rα, stimulates glutamine metabolism to support cell growth in breast cancer cells." (PMID 34769439, 2021). "In 4 T1 breast cancer cells, IL4Rα enhanced tumor growth by mediating IL4-related enhancement of glucose and glutamine metabolism." (PMID 33419470, 2021). "It is reported that IL4Rα is overexpressed in human breast cancer and silencing of IL4Rα attenuated growth of metastatic breast cancer cells." (PMID 31540495, 2019). "The IL-4 receptor is significantly expressed in breast cancer while IL4R is compulsory for the actions of IL-4 on cancer cells." (PMID 30648081, 2018). "IL-4 down-regulated the surface expression of IL-4Rα on one human renal cancer cells, gastric cancer cells and breast cancer cells, and thus showed much higher cell growth-inhibitory effects of IL-4 than IL-4R non expressed cells." (PMID 26993600, 2016). "IL-4, a Th2 cytokine, has been showed increased in the microenvironment of breast carcinomas, and IL-4R was overexpressed by breast cancer cells themselves." (PMID 26313265, 2015). "IL-4 inhibits tumour growth by its anti-angiogenic effect and inhibits growth and induces apoptosis of breast cancer cell lines in the presence of IL-4R." (PMID 16842617, 2006). "The aim of this study was to evaluate any role of specific SNPs in the interleukin genes IL1A, IL1B, IL1RN, IL4R, IL6 and IL10 in predisposition to breast cancer susceptibility and severity." (PMID 16842617, 2006). "IL4 receptor is significantly expressed in breast cancer and it has been shown that IL4R is required for actions of IL4 on breast cancer cells including the inhibition of growth and induction of apoptosis." (PMID 16842617, 2006). "Type II IL4R is expressed on epithelial cancer cells, including breast cancer, responds to stimulation by either IL4 or IL13, and its elevated expression is associated with breast cancer metastasis." (PMID 40663259, 2025).
breast cancer (continued). "There are some genetic association studies conducted on Bangladeshi Breast cancer and cervical cancer population to evaluate susceptible single nucleotide polymorphisms of INSIG2, HLA-DRB1, GCNT1P5, IL1β, IL4R, IL6, FGFR2, CYP1A1, ESR1 genes and disease outcome." (PMID 40920780, 2025). "CCL2 can help prostate tumor growth and bone metastasis by recruiting macrophages and osteoclasts and macrophages also promote breast cancer bone metastases in an IL-4R-dependent manner, and inhibition of IL-4R effectively reduces the occurrence of bone metastases." (PMID 38464516, 2024). "Also, macrophages promote breast cancer-induced bone metastasis through the IL-4 receptor (IL-4R), while monocyte/macrophage-restricted IL-4R ablation reduces the occurrence of this disease." (PMID 39595017, 2024). "IL4R promotes breast cancer growth and LILRB3 can block antitumor immune activation." (PMID 36980301, 2023). "In advanced breast cancer, monocyte-derived macrophages promote bone metastasis growth in an IL4R signaling-dependent manner, indicating that inhibition of macrophages and IL4R may lead to a new potential therapy targeting bone metastasis." (PMID 35994202, 2022). "Blocking of IL4Rα also induced the apoptosis of breast cancer cells." (PMID 33419470, 2021). "In summary, anti-VCAM1 and anti-IL4Rα aptamers specific to VCAM-1 and IL4Rα receptors biomarkers that are overexpressed in 4T1-Luc2 tumor bearing mice were used as diagnostic and therapeutic tools for breast cancer." (PMID 32751068, 2020). "Recent studies of IL-4/IL-4 receptor (IL-4R) signaling in breast cancer cells in vitro and in vivo show enhanced cell survival and proliferation via signal transducer and activator of transcription (STAT)/protein kinase B (AKT)/mitogen-activated protein kinase (MAPK) signaling." (PMID 27169366, 2016). "A recent report showed that the type II IL4R was expressed and activated in human breast cancer and the metastatic capacity was decreased by knocking down IL4Rα, therefore inactivating Erk1/2, Akt and mTor induced reduction in breast cancer proliferation and survival." (PMID 26313265, 2015). "The IL-4/IL-4R interaction enhanced the proliferation and survival of breast cancer cells in vitro." (PMID 26313265, 2015). "The aim of this study was to evaluate polymorphisms in specific cytokine genes [IL1A +4845G>T, IL1B -511C>T, IL1B +3954C>T, IL1RN +2018T>C, IL4R -1902A>G, IL6-174G>C and IL10-1082G>A] in a case control model to determine any associations with breast cancer susceptibility, severity and survival." (PMID 16842617, 2006). "Our data on the IL4R polymorphism +1902A>G has shown no overall association with breast cancer susceptibility, severity or survival." (PMID 16842617, 2006). "The results from our study do not support the hypothesis that the cytokine polymorphisms studied [IL1A +4845G>T, IL1B -511C>T, IL1B +3954C>T, IL1RN +2018T>C, IL4R -1902A>G, IL6-174G>C and IL10-1082G>A] are associated with breast cancer susceptibility and severity." (PMID 16842617, 2006). "Specifically, PYK2 ablation inhibits Notch1 signaling and consequently reduces CCL2 secretion by breast cancer cells, and concurrently reduces the levels of CCR2, CXCR4, IL‐4Rα, and Stat6 activation in macrophages." (PMID 35092356, 2022). "In this article, we investigated anti-VCAM-1 ssDNA aptamer and anti-IL4Rα RNA aptamer, conjugated to SPIO nanoparticles, for the diagnosis and treatment of breast cancer cells." (PMID 32751068, 2020). "In human breast cancer, cathepsin D (CTSD), IL4 receptor (IL4R), mucin-1 (MUC1, CD227), and serine protease 3 (PRSS3) may serve as valuable biomarkers for the diagnosis and treatment of breast cancer." (PMID 35787690, 2022). "Both IL4RPep-1-FITC (~0.59%) and NSSSVDK-FITC (~0.53%) showed no binding in 4T1 cells (In vitro IL4R-expression-lacking mouse breast cancer cells)." (PMID 36009525, 2022).
breast cancer (continued). "In vitro studies further showed significantly higher binding of the [AP1-V12]6 polymer to IL-4R highly expressed H226 lung cancer and MDA-MB-231 human breast cancer cells than to IL-4R negative H460 cells." (PMID 24339977, 2013). "Polymorphisms within key interleukin genes (IL1A, IL1B, IL1RN, IL4R, IL6 and IL10 do not appear to play a significant overall role in breast cancer susceptibility or severity." (PMID 16842617, 2006). "Taken together, these data suggest that during breast cancer recurrence, tumor cell-derived OPN recruits macrophages into the tumor and, together with tumor cell-derived IL-4, further accentuates some of their pro-tumorigenic characteristics such as IL-4R expression to facilitate recurrence." (PMID 39448577, 2024). "Additionally, as the mouse IL‐4R/IL‐4 interaction is species‐specific in that mouse IL‐4 does cross‐react with human IL‐4R, we were unable to perform cytotoxicity assays with DABIL‐4, either against human breast cancer cell lines in vitro or with in vivo murine models of human breast cancer." (PMID 33682324, 2021).
helminth infection (28 papers, 2011 to 2025). "Surface expression of the MR, IL-4Rα, and PD-L2 has previously been associated with AAMφs in distinct helminth infections." (PMID 25664320, 2015). "Alternative activation of macrophages during helminth infection has been linked to signaling through the IL-4 receptor alpha chain (IL-4Rα), but the potential effects of antibodies on macrophage differentiation have not been explored." (PMID 24244174, 2013). "Arg1 expression during helminth infection is normally associated with an AAM phenotype dependent upon IL-4Rα signaling." (PMID 24244174, 2013). "Further studies showed reduced neutrophil cell death following helminth infection and increased proliferation, which was dependent on IL-4R signaling." (PMID 40196466, 2025). "IL-4 and IL-13 are produced during helminth infections, which in turn activates the IL-4R/STAT signalling pathway." (PMID 37705099, 2023). "IL-4Rα signaling is crucial for the accumulation of GATA3+ Tregs in the inflamed intestine during helminth infections; therefore we analyzed the Th2 cytokines IL-4, IL-5, and IL-13 secreted by LPMCs in the colon." (PMID 34336843, 2021). "The majority of IL-4Rα−/−IL-5−/− mice contained active adult worm infections and frequency of infection was significantly higher compared with WT or IL-4Rα−/− mice (15/18 mice, versus 5/19 WT and 6/16 IL-4Rα−/− mice, χ2 statistic: 70.61, p < 0.0001)." (PMID 32571840, 2020). "In comparison, a significantly higher proportion (9/11) of IL-4Rα−/−CCR3−/− double-knockout mice yielded adult worm infections (χ2 statistic: 70.61, p < 0.0001)." (PMID 32571840, 2020). "The cytokines interleukin (IL)-4 and IL-13, signaling via the IL-4 receptor (IL-4R), orchestrate type 2 immunity to helminth infections and toxins." (PMID 32139893, 2020). "Having discussed the evidence suggesting an inhibitory role of IL-4R signaling on neutrophils, it seems awkward that neutrophils have been reported to play a significant role in type 2 immunity against helminth infections." (PMID 31708926, 2019). "In contrast to the apparent importance of neutrophils in helminth infections, there is accumulating evidence that IL-4R signaling by IL-4 and IL-13 inhibits neutrophil effector functions." (PMID 31708926, 2019). "Mice with a myeloid cell-specific knockout of IL-4 receptor-α (IL4Rα) were found to lack M2 macrophage development in mouse models of helminth infection and in Th2 cell-mediated inflammation, where IL-4 has a major role." (PMID 30546316, 2018). "Our data demonstrates that IL-4/IL-4Rα activated AAMφ orchestrate eosinophil immunity to filarial tissue helminth infection." (PMID 29547639, 2018). "It has long been known that IL-4Rα-mediated signaling is the pivotal component of the protective immune response to helminth infection, being required to generate the appropriate innate and adaptive type two cellular responses." (PMID 30238872, 2018). "Interleukin(IL)-4 and IL-13 can induce alternative activation of Mφ populations in diverse tissue sites during helminth infections via the IL-4 receptor (IL-4R)." (PMID 29547639, 2018). "Taken together, our data presents a strong case for a necessity of sustained IL-4Rα mediated signaling to maintain the stability of established type 2 immune responses during helminth infections." (PMID 28651009, 2017). "Our findings expand on this understanding by demonstrating that production of SP-D following helminth infection is significantly dependent on key protective immune responses against N. brasiliensis; namely IL-4/IL-13 signaling via IL-4Rα." (PMID 26900854, 2016). "Other studies have shown that Tregs need IL-4Rα to control inflammation during worm infection." (PMID 33628844, 2021). "Collectively, this study identifies a previously unappreciated origin of Th2 cells after helminth infections and suggests that targeting IL-4R signaling on T reg cells may promote Th2 cells, simultaneously curbing T reg cells, to enhance antihelminth immunity." (PMID 28507062, 2017).
helminth infection (continued). "The interplay between IL‐33R and IL‐4Rα signaling may be particularly important during helminth infection." (PMID 27592711, 2016). "Similarly, we observe IL-4Rα induction of insulin like growth factor (IGF-1) during helminth infection as previously demonstrated in vitro." (PMID 25028340, 2014). "However, similar to the ability of IL-4 and IL-13 to induce the alternatively activated phenotype in macrophages in the context of helminth infections, fungus-induced Arg1 was also found to be at least partially dependent on IL-4Rα/STAT6." (PMID 21246055, 2011). "For example, IL-4 could signal through IL-4Rα to trigger specialized macrophage activation, promoting the mitigation of helminthic infection and tissue repair in the liver and lung, or reduce the production of C-reactive protein (CRP) by human primary hepatocytes." (PMID 34307393, 2021). "However, it remains unknown whether intestinal macrophages depend on IL4Rα signalling for their education during helminth infection." (PMID 34329367, 2021). "Adding to previous reports that have defined a restraining role for IL-4Rα on Foxp3+ Treg cells in vivo, we now present complementary evidence indicating that this receptor is equally needed, in full, in vivo for Foxp3+ Treg cell ability to control inflammation during helminth infections." (PMID 30379806, 2018). "Many laboratories have demonstrated that these markers are also IL4Rα dependent in vivo and these have become reliable indicators of M(IL4), especially in the context of type 2 inflammation and helminth infections." (PMID 34329367, 2021). "It is believed that IL-4Rα signaling is crucial to up-regulate GATA3 in Tregs and promote the accumulation of GATA3+ Tregs in the inflamed intestine during helminth infection." (PMID 34336843, 2021). "In contrast, in uninfected mice whose ability to upregulate Th2 signaling is impaired (IL-4−/−, STAT6−/−, or IL-4Rα−/− genotype), these numbers remained low and did not rise above baseline levels after helminth infection." (PMID 37294277, 2023). "Helminth infection did not augment the generation of IL-4 or TGF-β by T cells within MLNs in the absence of IL-4Rα expression, narrowing down Th2-dependent TGF-β generation into a T cell–intrinsic regulatory circuit or developmental pathway." (PMID 37294277, 2023). "IL-13 and/or IL-4, which both use the IL-4Rα chain, are also central to resistance against many if not most helminth infections." (PMID 25028340, 2014). "Intriguingly, the reprogramming of macrophages by helminth-specific antibodies did not require IL-4Rα signaling, indicating that antibody activation of macrophages during helminth infection represents a novel pathway of alternative macrophage differentiation." (PMID 24244174, 2013). "Thus, there remains no clear exploration of the role of IL4Rα in the education of colonic macrophages during either steady state or in an inflamed gut environment during helminth infection." (PMID 34329367, 2021). "However, because IL-4R-independent AAMφ differentiation has also been demonstrated in helminth infections, we examined Mφ development in either Severe-combined (SCID; no functional T or B cells) or IL-4Rα deficient (IL-4/IL-13 non-responsive) BALB/c mice." (PMID 29547639, 2018). "Irrespective of the degree of IL-4Rα deletion within the Foxp3+ Treg cell population, mice showed exacerbation of immune effector responses with aggravated tissue pathology in tissue-dwelling helminth infections (Schistosoma mansoni or Nippostrongylus brasiliensis)." (PMID 30379806, 2018). "Thus, helminth infection promotes survival of recipient T cells in the spleen and MLNs in WT but not IL-4−/−, STAT6−/−, or IL-4Rα−/− BMT recipient mice when they receive WT C57BL/6 donor cells." (PMID 37294277, 2023).
helminth infection (continued). "We next tested a large cohort of BMT mice for CD3 and H2b expression, discovering that in WT mice a significant portion of CD3+ cells did not stain for H2b− following helminth infection but that almost all CD3+ cells from IL-4−/−, STAT6−/−, or IL-4Rα−/− BMT recipients did." (PMID 37294277, 2023).